VDAC1P2 (voltage dependent anion channel 1 pseudogene 2)
Synonyms: formerly VDAC1LP
Gene: Processed pseudogene on chromosome X (49,632,500 to 49,633,349, reverse strand). Ensembl gene ENSG00000213856.
Diseases named in the same sentence as VDAC1P2 in open-access papers:
VDAC1P2 is named in the same sentence as 1 disease in open-access papers, as found by Europe PMC text mining. Sharing a sentence is not in itself a finding about the gene and the disease. The quoted sentences say what the papers report.
tumor (1 paper, 2023). "Specifically, the expression profile of VDAC1P1 and VDAC1P2 in this analysis largely mirrors that of VDAC1, in both healthy and tumor tissues." (PMID 37344914, 2023).